SAMM50 (SAMM50 sorting and assembly machinery component)
Description:
Plays a crucial role in the maintenance of the structure of mitochondrial cristae and the proper assembly of the mitochondrial respiratory chain complexes. Required for the assembly of TOMM40 into the TOM complex.
Synonyms: TRG-3; SAM50; CGI-51; YNL026W; OMP85; TOB55
Tractability: PROTAC: ubiquitination databases record sites on it; its protein half-life has been measured.
Gene: Protein-coding gene on chromosome 22 (43,955,399 to 44,010,531, forward strand). Ensembl gene ENSG00000100347.
Subcellular location: Mitochondrion outer membrane; Cytoplasm; Mitochondrion
Subcellular location (Human Protein Atlas): Mitochondria
Pathways (Reactome):
Organelle biogenesis and maintenance: Cristae formation
Protein localization: Mitochondrial protein import
Signal Transduction: RAC2 GTPase cycle
Gene Ontology:
Molecular function: protein binding
Biological process: cristae formation; protein import into mitochondrial matrix; inner mitochondrial membrane organization; protein insertion into mitochondrial outer membrane
Cellular component: extracellular exosome; membrane; MIB complex; mitochondrial outer membrane; mitochondrion; SAM complex; cytoplasm; outer membrane
Genetic constraint (gnomAD): Loss-of-function variants: 23 observed, 37.1 expected, observed/expected ratio (o/e) 0.62, 90% interval 0.44 to 0.88. The upper end of that interval is the gene's LOEUF score, 0.88, which puts it in group 3 of 6, group 1 being the genes least tolerant of losing a copy. Missense variants: 342 observed, 391.95 expected, observed/expected ratio (o/e) 0.87, 90% interval 0.8 to 0.95. Synonymous variants: 137 observed, 148.7 expected, observed/expected ratio (o/e) 0.92, 90% interval 0.8 to 1.06.
Homologues: Orthologues: guinea pig SAMM50 (96% identical), mouse Samm50 (96% identical), chimpanzee SAMM50 (96% identical), macaque SAMM50 (96% identical), dog SAMM50 (95% identical), rat Samm50 (95% identical), pig SAMM50 (93% identical), tropical clawed frog samm50 (88% identical), zebrafish samm50 (84% identical), zebrafish samm50l (78% identical), rabbit SAMM50 (69% identical), Drosophila melanogaster CG7639 (34% identical), and 1 more.
Diseases named in the same sentence as SAMM50 in open-access papers:
SAMM50 is named in the same sentence as 39 diseases in open-access papers, as found by Europe PMC text mining. Sharing a sentence is not in itself a finding about the gene and the disease. The quoted sentences say what the papers report.
Hepatic steatosis (7 papers, 2013 to 2025). Steatosis is a term used to denote lipid accumulation within hepatocytes. "Our findings extend the association of SAMM50 variants to normal-weight individuals and provide further evidence supporting a causal role for SAMM50 in hepatic steatosis." (PMID 40677695, 2025). "The present study demonstrated that two single nucleotide polymorphismss (rs738491 and rs2073082) of the SAMM50 gene are associated with susceptibility to and severity of fatty liver in a Chinese Han population." (PMID 33728819, 2021). "Our results confirm the association between the SAMM50 rs738491 and rs2073082 polymorphisms and the risk of fatty liver in a Chinese cohort." (PMID 33728819, 2021). "However, the contribution of SAMM50 polymorphisms to the occurrence and severity of fatty liver in the Chinese Han population has rarely been reported." (PMID 33728819, 2021). "However, the contribution of SAMM50 polymorphisms to the occurrence and severity of fatty liver in the Chinese Han cohort has rarely been reported." (PMID 33728819, 2021). "Our objective was to test whether this, and other polymorphisms previously related to fatty liver disease in HIV infection linked to SAMM50 or LPPR4 genes, influence liver fibrosis progression in HIV/HCV-coinfected individuals." (PMID 27973562, 2016). "Since mitochondria play a key role in lipid metabolism and non-alcoholic and alcoholic fatty liver disease are also marked by oxidative stress, a crucial involvement of SAMM50 in the pathomechanism leading to fatty liver disease is conceivable." (PMID 36499681, 2022). "This final list includes six genes associated with ALT elevation and/or hepatic steatosis (MAPK10, CPN1, TRIB1, PNPLA3, SAMM50 and MICAL3)." (PMID 23813869, 2013). "Since mitochondria are known to play a key role in the pathogenesis of fatty liver disease, genetic variation in SAMM50 might be related to this process." (PMID 36499681, 2022).
non-alcoholic fatty liver disease (7 papers, 2016 to 2025). "Background and aim: Several studies have identified that three SAMM50 polymorphisms (rs2073082, rs738491, rs3761472) are associated with an increased risk of non-alcoholic fatty liver disease (NAFLD)." (PMID 37760857, 2023).
Cirrhosis (3 papers, 2016 to 2025). A chronic disorder of the liver in which liver tissue becomes scarred and is partially replaced by regenerative nodules and fibrotic tissue resulting in loss of liver function. "By contrast, the other SNPs evaluated here, linked to SAMM50 and LPPR4 genes, which were previously associated with FLD in the HIV-infected population, have not shown any association with cirrhosis or significant LSP in our study." (PMID 27973562, 2016).
liver fibrosis (3 papers, 2016 to 2025). "Our research highlights a significant association of SAMM50-rs2073080 with the progression of NAFLD to hepatic fibrosis, and the in vitro experiments further corroborated these findings." (PMID 39898988, 2025). "Our research highlights the significant association of SAMM50-rs2073080 with the progression of NAFLD to hepatic fibrosis." (PMID 39898988, 2025). "Furthermore, the current research on the relationship between SAMM50 genetic polymorphism and liver fibrosis is inconsistent." (PMID 37760857, 2023). "In vitro studies using human hepatic stellate cells indicated the upregulation of SAMM50-rs2073080 in the liver fibrosis model." (PMID 39898988, 2025). "Nevertheless, it is important to note that the current body of research concerning the relationship between SAMM50-rs2073080 and liver fibrosis is limited." (PMID 39898988, 2025). "In addition, liver fibrosis-related mRNAs such as α-SMA and collagen I were significantly up-regulated in LX-2 cells overexpressed by SAMM50-rs2073080, indicating that SAMM50-rs2073080 overexpression would accelerate the progression of liver fibrosis." (PMID 39898988, 2025).
steatosis (3 papers, 2021 to 2025). Increased lipid within the cytoplasm of cells. "In addition, GWAS fine mapping identified potential causal variants in GATAD2A, SUGP1, and MAU2, while TWAS fine mapping implicated SAMM50 as a driver of steatosis in normal-weight individuals, possibly through changes in gene expression." (PMID 40677695, 2025). "Immunohistochemistry (IHC) staining analysis indicated that SAMM50 expression has an upregulation trend in the liver of patients with steatosis compared with that in the normal liver." (PMID 33728819, 2021).
cardiac hypertrophy (2 papers, 2021 to 2022). "To further elucidate the underlying mechanism of Samm50 in the regulation of myocardial hypertrophy, we first detected the expression of Pink1 and Parkin in response to Ang II stimulation." (PMID 34631840, 2021). "Samm50 significantly inhibited angiotensin II-induced autophagy activation, as manifested by decreased mitophagy protein levels; however, the inhibition of mitophagy by Vps34 inhibitor or PINK1 knockdown abolished the protective effect of Samm50 deficiency on cardiac hypertrophy." (PMID 36132224, 2022). "However, the protective role of Samm50 deficiency against cardiac hypertrophy was abolished by inhibiting mitophagy through Vps34 inhibitor or Pink1 knockdown." (PMID 34631840, 2021). "The results revealed that the Vps34 inhibitor largely diminished the protective effect of Samm50 deficiency on Ang II-induced hypertrophy, indicating the beneficial function of mitophagy in cardiac hypertrophy and that Samm50 regulates cardiomyocyte hypertrophy by inhibiting mitophagy." (PMID 34631840, 2021). "Given that Samm50 is associated with mitochondrial homeostasis and mitophagy, we explored whether Samm50 aggravates cardiac hypertrophy by affecting mitochondria function." (PMID 34631840, 2021). "Here, we identified a member of mitochondrial SAM complex, Samm50, which positively regulates cardiac hypertrophy involving mitophagy." (PMID 34631840, 2021). "Further understanding the mechanism by which Samm50 regulates mitophagy in cardiac hypertrophy is important for exploring the new strategies for treatment." (PMID 34631840, 2021). "In conclusion, our present study shows Samm50 aggravates cardiac hypertrophy by regulating the Pink1-Parkin signaling and further clarifies the relationship between mitophagy and cardiac hypertrophy." (PMID 34631840, 2021). "Collectively, we first discovered that Samm50-mediated mitophagy in cardiac hypertrophy was largely dependent on Pink1-Parkin signaling." (PMID 34631840, 2021). "To evaluate the role of mitophagy in Samm50-mediated cardiac hypertrophy, we introduced an autophagy inhibitor into the Samm50-depleted cardiomyocyte prior to Ang II stimulation." (PMID 34631840, 2021). "Then, Samm50 overexpression exhibits enhanced induction of cardiac hypertrophy marker genes and cell enlargement in primary mouse cardiomyocytes by qPCR and immunofluorescence analysis, respectively." (PMID 34631840, 2021). "To determine whether Samm50 expression is associated with cardiac hypertrophy, we performed the TAC mice model and found the mRNA, and protein levels of Samm50 were remarkably decreased in response to pressure overload." (PMID 34631840, 2021). "Although Samm50 is a key regulatory factor of Pink1 and might affect mitophagy, whether it regulate the Pink1-Parkin pathway and involve in cardiac hypertrophy remains poorly understood." (PMID 34631840, 2021). "We further observed that Samm50 depletion attenuates cardiomyocyte hypertrophy and promotes mitophagy, indicating that Samm50 might inhibit mitophagy to exacerbate cardiac hypertrophy." (PMID 34631840, 2021). "In our study, we found that the expression of Samm50 was significantly downregulated in vivo and in vitro cardiac hypertrophy model, indicating that the changes of Samm50 maybe play a role in cardiac hypertrophy." (PMID 34631840, 2021). "Agreed with the previous study, our results showed that Samm50 could directly interact with Pink1 in the cardiac hypertrophy model." (PMID 34631840, 2021). "We first found that Samm50 is a key positive regulator of cardiac hypertrophy, for western blot and real-time quantitative PCR detection revealed Samm50 was downregulated both in pressure-overload-induced hypertrophic hearts and Ang II-induced cardiomyocyte hypertrophy." (PMID 34631840, 2021). "In this study, we found that Samm50 was downregulated in the cardiac hypertrophy model." (PMID 34631840, 2021). "Our results showed that Samm50 exacerbates cardiac hypertrophy by inhibiting mitophagy." (PMID 34631840, 2021).
cardiac hypertrophy (continued). "To evaluate whether Pink1 is required for Samm50-mediated cardiac hypertrophy, we interfered with the expression of Pink1 in the absence of Samm50." (PMID 34631840, 2021). "Meanwhile, knockdown Samm50 could ameliorate cardiac hypertrophy." (PMID 34631840, 2021). "However, whether Samm50 participates in the cardiac hypertrophy process remains unclear." (PMID 34631840, 2021).
liver disease (2 papers, 2016 to 2022). "Minor allele frequency (MAF) of SAMM50 rs3827385 were 18.8% and 18.0% in healthy controls and controls with alcohol abuse but absent significant liver disease, respectively, which was comparable to the published MAF of 21.6%." (PMID 36499681, 2022). "The same effect could be noted for both SAMM50 minor variants but the homozygous minor variants failed statistical significance against both control groups without liver disease." (PMID 36499681, 2022). "Therefore, SAMM50 seems to be an interesting gene in relation to liver disease." (PMID 36499681, 2022). "On the contrary, others SNPs associated with FLD in the HIV-infected population such as SAMM50 rs738491 and LPPR4 rs12743824 do not seem to have a relevant role on liver disease evolution in these patients." (PMID 27973562, 2016). "Similarly, the MAFs of SAMM50 rs3761472 were 19.6% and 17.9%, respectively, in both control cohorts without liver disease, which corresponded to the published MAF of 18.8%." (PMID 36499681, 2022).
sarcopenia (2 papers, 2025 to 2026). Progressive decline in muscle mass due to aging which results in decreased functional capacity of muscles. "From a clinical perspective, the potential of ENSA, FAM43A, MDH2, NUBP1, SAMM50, and TM2D1 as biomarkers is promising, as they may be measurable in peripheral blood or muscle biopsy specimens to support early screening and individualized diagnosis of AS patients at risk of sarcopenia." (PMID 41204493, 2025).
breast carcinoma (1 paper, 2022). "Moreover, in the case of control samples, we found overexpression of the proteins: PRDX2, PRDX5 and AIFM1 involved in ROS; TUSC2 in PMM; ALKBH7, RHOT1, SAMM50, IMMT and HSPA9 in the MMO; and FUNDC2 in MIT compared to luminal A and basal-like breast cancer tumors." (PMID 35327574, 2022).
COVID-19 (1 paper, 2020). A disease caused by infection with severe acute respiratory syndrome coronavirus 2. "Several mitochondrial genes, for instance NDUFA10, NDUFAF5, and SAMM50 were downregulated in COVID-19-affected lung." (PMID 33173052, 2020).
fibrosis (1 paper, 2025). the formation of excess fibrous connective tissue in an organ or tissue in a reparative or reactive process. "SAMM50-rs2073080 was upregulated in the NAFLD-associated fibrosis model." (PMID 39898988, 2025).
Insulin resistance (1 paper, 2022). Increased resistance towards insulin, that is, diminished effectiveness of insulin in reducing blood glucose levels. "According to the results of this meta-analysis, A allele of rs2143571, rs3761472, and rs738491 in the SAMM50 gene might be related to mitochondrial dysfunction and insulin resistance, leading to the NAFLD development." (PMID 35866791, 2022).
liver cancer (1 paper, 2019). An epithelial or non-epithelial malignant neoplasm that arises from the liver. "At the 22q region, PNPLA3 incorporate mostly in the phospholipid metabolism and lipase activity pathways, SAMM50 enriched in the mitochondrial assembly pathway (GO cellular components), and PARVB enriched in the liver cancer pathway." (PMID 31311600, 2019).
Obesity (1 paper, 2022). Accumulation of substantial excess body fat. "This study suggests that SAMM50 has a potential role in obesity and related metabolic disorders through the thermogenesis of beige adipocytes by targeting mitochondrial dynamics." (PMID 35743205, 2022). "Especially, SAMM50, in these roles, may be involved in improving obesity." (PMID 35743205, 2022).
ovarian carcinoma (1 paper, 2022). A malignant neoplasm originating from the surface ovarian epithelium. "Our result reveals multiple candidate protein biomarkers, including SAMM50 and IMMT, to be causally associated with response to treatment in ovarian cancer." (PMID 35931981, 2022).
tumor (40 papers, 2011 to 2025). "Indeed, RNA expression level and protein abundance of both SAMM50 and IMMT in the same tumor samples showed poor correlation (cor < 0.25)." (PMID 35931981, 2022).
cancer (10 papers, 2010 to 2025). A tumor composed of atypical neoplastic, often pleomorphic cells that invade other tissues. "The previous study has suggested that Samm50-mediated mitophagy is dependent on the Pink1-Parkin pathway under cancer conditions." (PMID 34631840, 2021). "Interestingly, granzyme B-mediated apoptosis is facilitated by interaction with SAMM50, suggesting a role for SAMM50 in cell death by reactive oxidative species and in lymphocyte-mediated cell death, e.g., of cancer cells." (PMID 36499681, 2022).
SAMM50 also shares sentences with these, for which no sentence is quoted: metabolic disorders (2 papers); viral hepatitis (2); alcohol abuse (1); alcoholic cirrhosis (1); alcoholic fatty liver disease (1); Cerebral ischemia (1); diabetes (1); gastric carcinoma (1); hepatocellular carcinoma (1); hyperthyroidism (1); hypertrophy (1); infarction (1); infection (1); intracerebral hemorrhage (1); ischemic stroke (1); liver abscesses (1); liver dysfunction (1); liver inflammation (1); oesophageal cancer (1); prostate carcinoma (1); rectal cancer (1); Stroke (1).